TEAD4 (TEA domain transcription factor 4)
Diseases named in the same sentence as TEAD4 in open-access papers (continued):
Sharing a sentence is not in itself a finding about the gene and the disease.
tumor (89 papers, 2006 to 2025). "According to this report, the generation of the short TEAD4 isoform is associated with tumor-associated exon skipping, which is a rather rare event." (PMID 38396900, 2024). "Meanwhile, the expression of CCL2 by tumor cells is also regulated by Yes-associated protein (YAP)/TEA domain family member 4 (TEAD4) dependence." (PMID 37663266, 2023). "Analysis on the clinical data from TCGA-BLCA datasets showed that TEAD4 expression was closely associated with tumor stage and grade." (PMID 35581606, 2022). "In vivo, silencing of TEAD4 by shRNA or CRISPR-Cas9 KO of both TEAD4 alleles significantly suppressed the tumor growth." (PMID 33893278, 2021). "TEAD4 can interact with NF-κB/p65, and it appears that excess YAP can disrupt NF-κB/p65 association with TEAD4, which could lead to tumor-suppressive effects." (PMID 39123485, 2024). "Cluster c7 expressed high level of Tead4, a key mediator of the Hippo signaling pathway, implicated in the promotion of epithelial-mesenchymal transition and metastatic cascade, and the axon guidance cue, Sema3a, implicated in tumor angiogenesis." (PMID 39457009, 2024). "Therefore, a systematic analysis of the DNA methylation status of the TEAD4-ΔN promoter in tumor samples can have diagnostic significance and provide guidance for treatment options." (PMID 38396900, 2024). "Moreover, a reduced level of TEAD4 promoter methylation in GC was significantly associated with poor outcomes, including larger tumor size and lower survival rates." (PMID 35739490, 2022). "TEAD4 is low expressed in the cell lines of cluster 7, which could be favorable since TEAD4 expression is associated with tumor onset and progression." (PMID 34006939, 2021). "Importantly, TEAD4 is associated with tumor recurrence and survival rate." (PMID 33893278, 2021). "Nevertheless, YAP/TEAD4/SP1-induced VISTA expression in tumor cells provides a new strategy for targeting VISTA for immune checkpoint therapy." (PMID 39875519, 2025). "This comparison showed a very high degree of overlap in the percentage of target loci where VGLL1 bound compared to those targets previously identified for TEAD1, TEAD2, TEAD3, and TEAD4 (p < 10e-370 for all 3 tumor cell lines)." (PMID 38912065, 2024). "Based on these findings, we further developed a linker peptide “glue” to force repressive condensation of TEAD4, which strongly reversed tumor progression." (PMID 39358623, 2024). "TEAD4, a downstream target protein of YAP in the Hippo pathway, has been implicated in tumor progression and osteoclast differentiation of BMM." (PMID 39129034, 2024). "TEAD4 is a tumor activator with the potential to induce signaling and regulate epigenetic profiles during embryonic development and tumorigenesis." (PMID 37856006, 2023). "Cytoplasmic TEAD4 was significantly higher in epithelial-rich B3 and C neoplasms (p = 0.002) and in advanced Masaoka–Koga stages (p = 0.05)." (PMID 37509515, 2023). "TEAD4, which serves as the de facto transcriptional executor of the pathway, is also upregulated in more aggressive neoplasms and advanced pathological stages." (PMID 37509515, 2023). "While increased nuclear YAP and TAZ are correlated with less aggressive tumors, higher cytoplasmic TAZ, TEAD4 and LATS1 are associated with high-grade and more advanced stage neoplasms." (PMID 37509515, 2023). "Whereas, TEAD4 was significantly higher in tumor samples compared to normal ovarian samples in both the TCGA and GSE26712 cohorts (p<0.05 p=5.8e-07)." (PMID 37342190, 2023). "Further analyses revealed that TEAD4 expression was remarkably correlated with N stage and tumor grade." (PMID 35581606, 2022). "TEAD4, TEA domain transcription factor 4, is important component in Hippo signaling pathway which is involved in controlling organ growth and inhibiting tumor through limiting cell proliferation and facilitating apoptosis." (PMID 35710932, 2022).
tumor (continued). "To examine the in vivo effect of TEAD4 on tumor metastasis, we designed a metastatic nude-mouse model by tail vein injection of TEAD4-knockdown BLCA cells." (PMID 35581606, 2022). "This critical role of the RAD21–YAP/TEAD4 complex in HGSOC tumor biology hints at its potential to be targeted therapeutically in HGSOC." (PMID 36201246, 2022). "Among these upregulated PRC2+-CGI genes, we found many well-defined oncogenes and genes encoding tumor-promoting factors such as MYB, TWIST1, SYK, TEAD4, FOXC1, and FGFR3." (PMID 33931649, 2021). "In combination with other findings in the current study, we proposed a positive feedback loop between NT5DC2 and TEAD4 in LMS tumour cells." (PMID 33993634, 2021). "Binding of YAP1/TEAD4 to ERα-bound enhancers is required for the induction of ERα target genes and tumor growth." (PMID 34145394, 2021). "For two proteins, YAP and TEAD4 higher expression was found in the case of higher clinical advancement of the tumor and in the presence of metastases." (PMID 34205023, 2021). "TEAD4 has been reported to modulate tumour progression through various pathways in several tumour types." (PMID 29667772, 2018). "Our clinical results and analyses revealed a possible tumour‐promoting role of TEAD4 in LAD, and we next aimed to confirm its molecular effect in the corresponding tumour cells." (PMID 29667772, 2018). "Considering its eligible effect on tumour proliferation and apoptosis, the pro‐metastatic role of TEAD4 seems more significant as revealed by transwell assay." (PMID 29667772, 2018). "Significantly higher abundance of TEAD4 mRNA was observed in HNSCC samples compared to their non-tumor counterparts." (PMID 30459528, 2018). "Co-expression of YAP/TEAD4-FL strongly induced EMT in two primary tumour cell lines as judged by increased levels of N-cadherin and Vimentin; however, the expression of TEAD4-S or RBM4 suppressed the induction of EMT markers." (PMID 27291620, 2016). "Its overexpression promoted tumor growth, but stable TEAD4 knockdown dramatically suppressed viability both in vitro and in vivo." (PMID 26805820, 2016). "TEAD4 overexpression stimulated proliferation in vitro and tumor growth in mice, while stable knockdown of TEAD4 inhibited proliferation in vitro and tumor growth in mice." (PMID 25970772, 2015). "Together, these data suggest that the transcription factor SP1 could be a transcriptional coregulator of YAP/TEAD4, which cooperatively promote tumorigenesis and tumor progression in CRC." (PMID 39875519, 2025). "Finally, the TEAD4 gene has also been found upregulated in various types of tumor tissues, where it has been shown to promote tumor growth and is associated with poor prognosis." (PMID 40862714, 2025). "First, although the cohort size is reasonable for a rare tumor entity such as TETs, it remains limited and precludes multivariate survival analyses to assess the potential prognostic value of TEAD4 expression while adjusting for relevant clinical and pathological cofactors." (PMID 40649713, 2025). "Importantly, GLUP treatment also appeared to have induced formation of TEAD4 condensates in the tumor tissues." (PMID 39358623, 2024). "Upon TEAD4 knockdown, there was a significant decrease in tumor size, weight, and volume in mice." (PMID 39224804, 2024). "It is reported that TEAD4 plays a tumor‐promoting role in BC." (PMID 37799806, 2023). "Intriguing, infiltrating immune cells including CD4+ T cells, NK (natural killer) cells, macrophages, and neutrophils were positively correlated with the expression of TEAD4 that implicates immune cells in bladder tumor microenvironment play a promoting role in tumor progression." (PMID 35602596, 2022). "Here, (R,S′)-MNF exerted a potent repression of the Hippo-YAP/TAZ signaling in PANC-1 tumor xenografts with the downregulation of genes encoding key mediators (TAOK1, MST2, MOBK1B), transcriptional regulators (WWTR1, TEAD4), and downstream pro-survival genes CYR61, BIRC2, and MCL1." (PMID 35256673, 2022).
tumor (continued). "Based on the univariate analysis, T stage, N stage, tumor stage and TEAD4 expression were identified as independent prognostic factors for OS; while only TEAD4 were evaluated and identified as independent prognostic factors for OS by both univariate and multivariate analysis." (PMID 35581606, 2022). "Silencing of TEAD4 suppresses cell proliferation in ccRCC cells in vitro and tumor growth in vivo." (PMID 35602596, 2022). "Elevated TEAD4 expression was observed in multiple tumour tissues." (PMID 33993634, 2021). "Furthermore, the damage of TEAD4-Yap1 interaction through TED-347 significantly inhibited the promoting effects of TEAD4 overexpression on tumor growth in vivo." (PMID 33517828, 2021). "Together with previous finding demonstrating its role in the transcription of mitochondrial-encoded OXPHOS genes, our finding that it also regulated nuclear-encoded OXPHOS genes suggests that TEAD4 is a master regulator of OXPHOS genes and mitochondrial functions in tumor cells." (PMID 33893278, 2021). "Furthermore, evidence of YAP–TEAD driving the expression of AP-1 targets has been shown to foster tumor growth, and AP-1 has been shown to co-occupy enhancer and promoter regions along with Tead4 in multiple cancer cell types." (PMID 31137701, 2019). "Besides, database search indicated a poorer clinical outcome in LAD patients with higher TEAD4 expression, revealing its potential tumour‐promoting role." (PMID 29667772, 2018). "To test whether endogenous TEAD4 also promotes TNBC cell proliferation and tumor growth, we stably knocked down TEAD4 in HCC1806 cells and HCC1937, and as expected, stable knockdown of TEAD4 increased the p27 protein levels and inhibited cell growth in vitro." (PMID 25970772, 2015). "Consequently, a novel EV delivery system (siT/MOF@EVs), which targets the tumor cell membrane–cytoplasm–mitochondria cascade, is engineered to codeliver TEAD4‐siRNA (siTEAD4) and a mitochondria‐targeting metal–organic framework (T/MOF) to overcome tumor heterogeneity." (PMID 40755363, 2025). "Notably, the expression of SPDEF and TEAD4 showed opposing trends in IV‐stage tumours." (PMID 40318012, 2025). "Additionally, a study has shown that TEAD4 acts as a tumor‐promoting factor role in ccRCC and may impose a significant impact on its progression." (PMID 37799806, 2023). "Restoring this TEAD4 isoform could inhibit tumor growth through repressing YAP signaling." (PMID 29050244, 2017). "Intriguingly, in three of the NSCLC specimens (samples 4, 5 and 7), the truncated TEAD4-S protein was the predominant isoform in normal tissues, but was almost completely eliminated in tumours, implying that the AS switch in TEAD4 could play a major role in the tumorigenesis of these patients." (PMID 27291620, 2016). "TEAD4, TBP, MYC, and ELF5 constituted the transcription factor regulatory network of C2 CPE+ tumor cells." (PMID 40230840, 2025). "For example, the collaborative activation of CYR61 by YAP/TEAD4 and TGFβ/SMAD2/3 exerts a tumor‐suppressive effect in hepatocellular carcinoma, counteracting malignant transformation and growth." (PMID 40895190, 2025). "Concurrently, the YAP/TEAD4–PAI 1 axis and HIF 1α signaling create a hypofibrinolytic milieu, synergizing with tumor-driven platelet activation to favor thrombus persistence." (PMID 41228207, 2025). "Here, we found that serum-stimulated PKCζ further enhanced the interaction of SP1 with TEAD4, which is in agreement with the activation of YAP/TEAD transcriptional activity upon serum stimulation to sustain tumor cell proliferation and survival." (PMID 39875519, 2025).
tumor (continued). "To verify the dependence of GLUP sensitivity on TEAD4 expression in tumor cells, we chose AGS, a human GC cell line with a low level of TEAD4 expression (upper), for further testing." (PMID 39358623, 2024). "Some TFs were specific for individual cell lines, others were shared between two cell lines, and a total of eight TFs were shared amongst all three tumor types, including TEAD1, TEAD2, TEAD3, TEAD4, GRHL2, RUNX2, AP1, and GATA6." (PMID 38912065, 2024). "In this study, we provide the first comprehensive evaluation of four Hippo pathway components’ (YAP, TAZ, TEAD4 and LATS1) expression pattern in a cohort of TETs, with interesting results regarding their levels and distribution within tumor cells." (PMID 37509515, 2023). "TEAD4 binds with YAP, TAZ, VGLL, and other transcription factors to modulate various tumour-related processes, including tumour cell proliferation, cell survival, tissue regeneration, and stem cell maintenance, in cancer via its transcriptional output." (PMID 36925653, 2023). "To further explore the unique prognostic and potential therapeutic value of TEAD4 in BLCA, we first surveyed the expression of TEAD4 between the tumor tissues and the adjacent normal tissues using TCGA-BLCA and GTEx datasets." (PMID 35581606, 2022). "Perhaps, it would be more appropriate to target tumor-specific or selective OXPHOS regulators, such as overexpressed PDKs, MPC2, or TEAD4." (PMID 34948229, 2021). "Selection experiments for the tumor‐relevant proteins MDM2 and TEAD4 yielded MDM2 binders and a novel class of TEAD‐YAP interaction inhibitors that perturbed the expression of a gene under the control of these Hippo pathway effectors." (PMID 32537835, 2020). "In particular, in lung cancer cells, which have lower TEAD4-S level compared with normal cells, TEAD4-FL activates transcription of N-cadherin and vimentin genes inducing EMT of tumor cells, while TEAD4-S suppresses EMT markers." (PMID 32244895, 2020). "It is reported that miR-375 exerts tumor suppressor function in GC through down-regulating the expression of three components of the Hippo pathway, YAP1, TEAD4, and CTGF." (PMID 32038526, 2019). "In EBV-positive gastric cancer, miR-375, which exerts tumor suppressor function through down-regulating YAP1, TEAD4, and CTGF, was down-regulated." (PMID 32038526, 2019). "Meanwhile, miR-375 targets YAP1, TEAD4, and CTGF and exerts tumor suppressor function involved in Hippo pathway." (PMID 29367737, 2018). "While PAR1 is the prototype member, overexpressed directly with the tumor aggressiveness, we address also hormone regulation of PAR1 and PAR2, as also YAP regulation by TEA domain 4 (TEAD4) on PAR2." (PMID 30400241, 2018). "Additionally, a recent study showed that a TEAD4 splicing variant (TEDA4-S, in which exon 3 is skipped by the tumor suppressor RBM4 protein) acts as a dominant negative TEAD4 isoform, and thereby both attenuates YAP activity and inhibits tumor-cell proliferation." (PMID 29565815, 2018). "A high TEAD4 level results in excessive transcription and expression of EMT proteins and therefore promotes tumour metastasis." (PMID 29667772, 2018). "We generated H157 cells with stable expression of YAP, YAP/TEAD4-FL, YAP/TEAD4-S or YAP/RBM4, and injected these cells subcutaneously into the flanks of nude mice to measure tumour growth." (PMID 27291620, 2016). "For example, the anti-TEAD4 antibody also detected overexpression of Flag-TEAD1–3 in HEK293T cells, indicating that we detected all TEAD proteins in tumor specimens using this antibody in general." (PMID 25970772, 2015). "Through the regulation of YAP1, TEAD4 binds to the TIAM1 enhancer region, thereby activates the expression of TIAM1 and subsequently increases the activity of RAC1 and induces the formation of invadopodia formation and promotes tumor metastasis." (PMID 40746611, 2025). "Narciclasine competes with TEAD4 to interact with YAP, thereby inhibiting tumor growth." (PMID 40895190, 2025).
tumor (continued). "Within this potential FFL, TEAD4 may drive the expression of miR-3662, which in turn suppresses PRDM5, tipping the balance toward tumor-promoting gene expression." (PMID 40862714, 2025). "Finally, to clarify the mechanisms of action of YAP/TEAD4/NRP1, we created xenograft tumor SCID mice." (PMID 39187525, 2024). "Taken together, these results indicate that VGLL4 and RFXANK can directly induce TEAD4 LLPS both in vitro and in vivo, and these condensates may function as repressors of transcription to eventually induce tumor cell apoptosis." (PMID 39358623, 2024). "In addition, TEAD4 expression was upregulated in TCGA BLCA samples and correlated with pT stage, tumor stage and tumor grade." (PMID 35581606, 2022). "Both mRNA and protein abundance of TEAD4 were significantly increased in HNSCC as compared to its non-tumor counterparts." (PMID 30459528, 2018). "In addition, evidence that TEA domain 4 (TEAD4) motifs are present within the hPar2 promoter is presented since the YAP oncogene, which plays a central part in tumor etiology, acts via the TEAD4 transcription factor." (PMID 30400241, 2018). "Furthermore, TEAD4 was identified in collaboration with KLF to promote cell proliferation and tumor growth in triple negative breast cancer (TNBC) partly by inhibiting p27 transcription." (PMID 26805820, 2016). "We also performed a tumorigenesis assay in nude mice and found that knockdown of TEAD4 significantly suppressed the xenograft growth of HCC1806; indeed, both tumor weights and volumes in the HCC1806-TEAD4sh#3 group were significantly less than those of HCC1806-Lucsh group." (PMID 25970772, 2015). "Thus TEAD4 and KLF5, in collaboration, promoted TNBC cell proliferation and tumor growth in part by inhibiting p27 gene transcription." (PMID 25970772, 2015). "Stable knockdown of TEAD4 in HCC1806 significantly inhibits DNA synthesis and tumor growth." (PMID 25970772, 2015). "To investigate whether YAP-mediated mTOR activation contributed to tumor initiation, we treated KEY primary cells with siRNAs targeting Yap/Taz and Tead1/Tead4 as well as small molecule mTOR (INK128) and YAP-TEAD (VT104) inhibitors, and observed significant reductions in clonogenic growth." (PMID 39779672, 2025). "The upregulation of TEAD4, a specific biomarker of LUAD_P05, may lead to excessive transcription and phosphorylation of the ERK protein, thereby accelerating the progression of tumour development and resulting in a poor prognosis." (PMID 39877290, 2025). "Matrix stiffness has been documented to regulate the expression of key tumor genes through various signaling pathways, including the integrin β1/Piezo1 activation/Ca2+ influx pathway, RhoA/ROCK pathway, YAP-POSTN-integrin mechanotransduction signaling, and YAP/TEAD4/ACADL axis." (PMID 40867005, 2025). "In MDA-MB-231 cells, all the tested genes were significantly downregulated in si-Bcl-2 condition, except for TEAD4, while only for TEAD2 transcript a significant modulation was observed in Bcl-2 silenced H460 cells, suggesting that Bcl-2 can affect Hippo pathway depending on the tumor histotype." (PMID 38755629, 2024). "Following the treatment of TED-347, which was able to suppress the interaction of TEAD4 and YAP1, the malignant behaviors of cells including proliferation, invasion, and migration were assessed by EDU staining, wound healing, and transwell assay in vitro, while tumor growth was measured." (PMID 33517828, 2021). "Intriguingly, through injecting KYSE-30 cells with OV-TEAD4 transfection or in combination with shRNA-SGK1 transfection into nude mice, we found that SGK1 silencing markedly interfered with the effects of TEAD4 overexpression on tumor volume and the expression of Ki67 and MMPs (MMP2 and MMP9)." (PMID 33517828, 2021).